QKI (QKI, KH domain containing RNA binding)
Diseases named in the same sentence as QKI in open-access papers (continued):
Sharing a sentence is not in itself a finding about the gene and the disease.
kidney diseases (1 paper, 2020). "We postulate that the modulation of the cellular transcriptome by interfering with QKI RNA-binding proteins represents a new and potent means of altering monocyte/macrophage responses and could aid in the prevention of kidney diseases." (PMID 34968236, 2020). "Our findings demonstrate that reduced expression of the alternative splice regulator QKI in the cells of myeloid lineage attenuates renal interstitial fibrosis, suggesting that inhibition of this splice regulator may be of therapeutic value for certain kidney diseases." (PMID 34968236, 2020). "Thus, QKI RNA-binding proteins may be of therapeutic value for certain kidney diseases." (PMID 34968236, 2020). "Whether QKI plays a role in kidney disease has hitherto not been investigated." (PMID 34968236, 2020).
neurodevelopmental disorder (1 paper, 2021). A behavioral and cognitive disorder with onset during the developmental period that involves impaired or aberrant development of intellectual, motor, or social functions. "RNA binding protein Quaking (QKI) is known for its broad function in pre-mRNA splicing and modification and its association with several neurodevelopmental disorders." (PMID 33397958, 2021). "The RNA-binding protein QKI belongs to the hnRNP K-homology domain protein family, a well-known regulator of pre-mRNA alternative splicing and is associated with several neurodevelopmental disorders." (PMID 33397958, 2021).
QKI also shares sentences with these, for which no sentence is quoted: meningioma (3 papers); Alzheimer disease (2); cardiac hypertrophy (2); kidney cancer (2); low grade glioma (2); oral squamous cell carcinoma (2); schwannoma (2); adenocarcinoma (1); amyotrophic lateral sclerosis (1); anal atresia (1); Anxiety (1); astroblastoma (1); blood cancers (1); brain cancer (1); Breast Invasive Carcinoma (1); breast tumor (1); Cognitive impairment (1); colon adenocarcinoma (1); colorectal adenocarcinoma (1); diabetic cardiomyopathy (1); diabetic nephropathy (1); esophageal squamous cell carcinoma (1); hereditary ataxia (1); hypercholesterolaemia (1); hyperlipidaemia (1); hyperplastic polyp (1); hypertriglyceridaemia (1); inflammatory bowel disease (1); kidney damage (1); large cell carcinoma (1).
A further 14 diseases each share a sentence with QKI in 1 paper.